RNU6-1057P (RNA, U6 small nuclear 1057, pseudogene)
Gene: Small nuclear RNA gene on chromosome 17 (20,290,257 to 20,290,358, forward strand). Ensembl gene ENSG00000252971.
Homologues: Orthologues: chimpanzee U6 (100% identical), macaque U6 (87% identical), dog U6 (57% identical), guinea pig U6 (57% identical). Paralogues in human: RNU6-21P (75% identical), RNU6-1077P (74% identical), RNU6-1292P (74% identical), RNU6-211P (74% identical), RNU6-723P (74% identical), RNU6-753P (74% identical), RNU6-1031P (73% identical), RNU6-106P (73% identical), RNU6-1084P (73% identical), RNU6-1152P (73% identical), RNU6-1244P (73% identical), RNU6-1260P (73% identical), and 1289 more.